ACTN4 (actinin alpha 4)
Diseases named in the same sentence as ACTN4 in open-access papers (continued):
Sharing a sentence is not in itself a finding about the gene and the disease.
lung carcinoma (continued). "We constructed a mutant plasmid with knockout of the PHD in PHF23 and found that PHF23 binds to ACTN4 via the PHD and inhibits the ubiquitination level of ACTN4, thereby promoting malignant biological behaviors of lung cancer cells." (PMID 37626047, 2023). "Interestingly, a recent study presented a similar regulatory mechanism in lung cancer, where plant homologous structural domain finger protein 23 (PHF23) enhanced the stability of alpha-actinin-4 (ACTN4) by inhibiting its interaction with E3 ligase." (PMID 39414762, 2024). "Given the role of OTUD3 as a deubiquitinase and its function in stabilizing GRP78 through deubiquitylation in lung cancer cells, we hypothesized that OTUD3 might deubiquitinate ACTN4 and stabilize it." (PMID 34380780, 2021). "ACTN4 was included in cluster 4 due to its significant increase in the brain tumor tissue but no apparent increase in the lung cancer tissue compared to the adjacent benign tissue." (PMID 25885339, 2015). "However, down-regulation of the ACTN4 gene expression does not increase the resistance of A549 lung cancer cells." (PMID 36476259, 2022). "The expression of ACTN4 (actinin, alpha 4), a cytoskeleton protein gene essential for cytoskeleton organization and cell motility, was significantly elevated in the metastatic brain tumor but not in the primary lung cancer tissue." (PMID 25885339, 2015).
hepatocellular carcinoma (15 papers, 2014 to 2025). A malignant tumor that arises from hepatocytes. "ACTN4 (α Actinin 4) is an actin-binding protein associated with cell motility and metastasis in breast, colorectal, pancreatic, hepatocellular carcinoma, and ovarian cancers." (PMID 24392146, 2014). "OTUD3 promotes lung tumorigenesis by stabilizing GRP78, while it stabilizes ACTN4 to drive hepatocellular carcinoma progression and metastasis." (PMID 38351178, 2024). "OTUD3 also influences hepatocellular carcinoma metastasis by mediating ACTN4 deubiquitination." (PMID 38288086, 2023). "In hepatocellular carcinoma, PDLIM1 competitively binds to ACTN4, disrupting the interaction between ACTN4 and F-actin, thereby activating the Hippo pathway and inhibiting metastasis." (PMID 39548074, 2024). "OTUD3 mediates Alpha-actinin 4 ACTN4 deubiquitination in HCC to stabilize it and promote hepatocellular carcinoma cell growth and metastasis." (PMID 37829187, 2023). "In hepatocellular carcinoma, TRIP13 regulated by miR-192-5p was shown to interact with and increase the expression of actinin alpha 4 (ACTN4), thus activating the AKT/mammalian target of rapamycin (mTOR) pathway to drive tumor progression." (PMID 36268276, 2022). "Additionally, miR-424-5p was also suggested to mediate the function of circRNAs and lncRNAs in human cancers, such as the promoter role of circRNA ACTN4 in cholangiocarcinoma and the promoted effect of lncRNA MYLK-AS1 in hepatocellular carcinoma." (PMID 37194024, 2023). "However, in hepatocellular carcinoma (HCC), PDLIM1 was poorly expressed, and overexpression of PDLIM1 in HCC competed for binding with the ACTN4, resulting in the dissociation of ACTN4 from F-actin." (PMID 37894409, 2023). "In addition, the ACTN4 and TRIP13 complex promotes EMT and tumor metastasis through the Akt signaling in hepatocellular carcinoma cells." (PMID 33363146, 2020). "For example, TRIP13 plays an oncogenic role in glioblastoma via the FBXW7/c-MYC pathway and induces hepatocellular carcinoma (HCC) cell migration, invasion, and metastasis through AKT/mTOR signaling via and interaction with ACTN4." (PMID 38012658, 2023).
glomerular disease (10 papers, 2004 to 2025). "To date, 20 different mutations have been reported for ACTN4-associated glomerular disease, most of them (nonsynonymous) missense mutations (HGMD professional 2022.2)." (PMID 36815115, 2022). "ACTN4 has been shown to be required for normal podocyte adhesion and mice deficient in ACTN4 have severe glomerular disease presumably due to this altered adhesiveness." (PMID 21085685, 2010). "As previously discussed, Myh9 and Actn4 encode proteins that are predominately expressed in the podocyte within the glomerulus and have been associated with genetic forms of glomerular disease." (PMID 19652713, 2009). "We have previously shown that dominantly inherited point mutations in the α-actinin-4 gene ACTN4 cause a form of human glomerular disease." (PMID 15208719, 2004). "These are the first studies demonstrating a role for ACTN4 in the distal nephron NaCl reabsorption and underscore the need for additional studies on this protein, known to be involved in glomerular disease." (PMID 39446130, 2024). "The Actin protein shows an amino acid identity of about 68% with human ACTN4, whereby the actin-binding domain in general as well as also single critical amino acids known to be affected in patients with glomerular disease, are especially conserved." (PMID 36815115, 2022). "Lower expression levels of ACTN4 were also reported in patients with glomerulopathies including FSGS." (PMID 36815115, 2022). "Importantly, the genes that encode several of these mRNAs (e.g. Actn4, Myh9) have previously been implicated in genetic forms of kidney disease or the encoded proteins have been shown to interact with gene products that have been shown to play a role in glomerular disease." (PMID 19652713, 2009). "Actn1-knockout mice are not viable while Actn4-deficient mice develop a severe glomerular disease indicating that Actn1 does not compensate for the loss of α-actinin-1." (PMID 32774516, 2020). "By contrast, mice homozoygous for Actn4 null alleles have glomerular disease, while heterozygous Actn4 null mice have no readily apparent phenotype." (PMID 15208719, 2004).
melanoma (10 papers, 2018 to 2023). A malignant, usually aggressive tumor composed of atypical, neoplastic melanocytes. "As TAM family members lead to phosphorylation of ACTN4, we queried whether the member most commonly associated with tumors, Axl, could drive melanoma progression." (PMID 36989239, 2023). "As we have shown that tyrosyl-directed phosphorylation of ACTN4 regulates amoeboid invasion of melanoma cells, we have sought the upstream regulators of this signaling pathway." (PMID 36989239, 2023). "We previously revealed that Tyro3 is important in melanoma migration via its phosphorylation and role in the regulation of ACTN4." (PMID 36989239, 2023). "In the other study it was shown that ACTN4 plays an important role in maintaining the amoeboid morphology of invasive melanoma, and thus promotes dissemination through collagen-rich matrices." (PMID 36278174, 2022). "Studies in melanoma have shown that ACTN4 promotes growth in melanoma cells by activating the NF-κB signaling pathway, and the transcriptional activation of NF-κB can induce the expression of ACTN4." (PMID 35568845, 2022). "Knockdown of ACTN4 in highly metastatic amoeboid melanoma WM1158 cells was found to lead to a switch from amoeboid to mesenchymal mode of motility." (PMID 36278174, 2022). "Next, we performed live cell tracking assay to determine the effects of Y265E and Y4/31/265E ACTN4 expression on cell motility of melanoma cells." (PMID 31664084, 2019). "To determine if the cellular localizations are specific to a cell type, we transiently transfected WT and mutant ACTN4 into melanoma cell line WM1158, as ACTN4 is critical for melanoma invasion." (PMID 31664084, 2019). "Finally, this mRNA vaccine was tested using B16 melanoma neoantigens (Pbk-Actn4) which resulted in delayed tumor growth." (PMID 36311701, 2022). "However, there is evidence suggesting that in melanoma cells cytoplasmic NF-kappaB is activated by ACTN4 indirectly via its physical interaction with cIAP1 and RIPK1." (PMID 31766144, 2019). "ACTN4 has also proven to be necessary for efficient amoeboid-type invasiveness of melanoma cells." (PMID 31766144, 2019). "Expression of ACTN4 was significantly upregulated in the melanoma invaded regions of the skin dermis, as compared with non-invaded skin areas." (PMID 36278174, 2022). "Finally, we investigated the therapeutic efficacy mRNA vaccine encoding neoantigens of PDZ-binding kinase (PBK) and actinin alpha 4 (ACTN4), which were identified from the B16F10 murine melanoma mutanomes." (PMID 36311701, 2022). "Again as in fibroblasts and melanoma cells, the K255E, T259I, and S262P ACTN4 all formed clusters in podocytes, whereas the Y4/31E/K255E, Y4/31E/T259I, and Y4/31E/S262P ACTN4 were no longer aggregated." (PMID 31664084, 2019). "Notably, a study revealed that TYRO3 knockdown suppressed melanoma cell migration and invasion, while TYRO3 overexpression led to the opposite outcomes via activation of the tyrosyl-phosphorylation of ACTN4, a member of the actin binding protein family involved in cancer cell motility." (PMID 32018224, 2020).
nephrotic syndrome (10 papers, 2014 to 2026). A collection of symptoms that include severe edema, proteinuria, and hypoalbuminemia; it is indicative of renal dysfunction. "Our patient with early-onset steroid-resistant nephrotic syndrome and end-stage renal disease harbored the novel variant, ACTN4 c.450C>G; p.Ile150Met." (PMID 41542112, 2026). "ACTN4 mutations are associated with nephrotic syndrome with a later onset in early adulthood, with a slower progression to ESRD after diagnosis." (PMID 40890712, 2025). "ACTN4 mutations are associated with nephrotic syndrome and renal dysfunction, with an onset in early adulthood." (PMID 40890712, 2025). "The actin crosslinking protein alpha-actinin-4 has been associated with human nephrotic syndrome and mutations in ACTN4 are associated with adult onset FSGS." (PMID 25352829, 2014). "These mutations could contribute to tumorigenesis by promoting cellular migration and invasion, and ACTN4 mutations are normally associated with the development of nephrotic syndrome." (PMID 40890712, 2025).
prostate carcinoma (10 papers, 2018 to 2025). A carcinoma that arises from epithelial cells of the prostate gland. "In prostate cancer, ACTN4 was found to be essential for WAVE2 (WASP family Verprolin-homologous protein)-mediated cancer cells motility and invasiveness." (PMID 34380780, 2021). "According to the Oncomine database for Tomlins Prostate Statistics (GSE6099), ACTN4 expression is elevated in prostate carcinoma compared to that in the prostate gland." (PMID 33363146, 2020). "Besides, CTCF (CCCTC-binding factor) was validated to activate HOXA11-AS transcription in prostate cancer cells and consequently to facilitate cell proliferation and migration by targeting miR-518b/ACTN4." (PMID 34715856, 2021). "The eight proteins highlighted in this study (KLK3, SORD, SPON2, IMPDH2, ACTN4, ATP1B1, HSPB1, and KHDRBS1) represent a signature associated with AR modulation during the transition from androgen-dependent to castration-resistant prostate cancers." (PMID 29966326, 2018). "ACTN4 may serve as a potential therapeutic target for prostate cancer." (PMID 32670437, 2020). "Elevated ACTN4 expression in prostate cancer upregulates LDHA expression, and other metabolic effects mediated by changes in ACTN4 expression have been suggested." (PMID 40980659, 2025). "In prostate cancer cells, HOXA11-AS induces actinin alpha 4 (ACTN4) expression through miR-518b sponging, leading to enhanced proliferation and migration of tumor cells." (PMID 32503307, 2020).
colorectal cancer (9 papers, 2015 to 2023). A primary or metastatic malignant neoplasm that affects the colon or rectum. "Using the co-IP/mass-spectrometry approach, ACTN4 was described as a protein partner of β-catenin in colorectal cancer cells upon the loss of E-cadherin." (PMID 31766144, 2019). "Disruption of ACTN4:integrin interactions facilitates EMT in colorectal cancer and increased expression of ACTN4 observed in filopodia increased motility and is correlated with regional lymph node metastasis." (PMID 33171868, 2020). "ACTN4 knockdown suppresses the migration and invasion of cancer cells, whereas its overexpression in colorectal cancer cells induces lymph node metastasis in immunodeficient mice." (PMID 25860875, 2015). "ACTN4 also increases cell motility and promotes lymph node metastasis in colorectal cancer." (PMID 33363146, 2020). "In addition, LIM domain kinase 1 (LIMK1), which is overexpressed in colorectal cancer, promotes cell motility and proliferation via Akt signaling, and ACTN4 is a downstream target gene of LIMK1 in colorectal cancer." (PMID 33363146, 2020). "ACTN4 was reported to enhance cell motility and promote lymph node metastasis of colorectal cancer." (PMID 25860875, 2015). "Cancer cells at the invasive front show increased expression of ACTN4 protein and EMT-like changes in colorectal cancer tissues." (PMID 36139525, 2022). "Increased motility and loosing epithelial features induced by the high expression of ACTN4 were also observed in NSCLC cells CL1-0 and colorectal cancer cells DLD-1." (PMID 31766144, 2019).
ovarian carcinoma (9 papers, 2008 to 2025). A malignant neoplasm originating from the surface ovarian epithelium. "Enhanced cytoplasmic expression of ACTN4 is related to increased cell motility and invasion and ACTN4 has recently been implicated in breast, lung, colorectal and ovarian cancers." (PMID 19055724, 2008). "Our findings align with previous research in ovarian cancer, specifically serous adenocarcinoma, where ACTN4 gene amplification has been linked to increased actinin‐4 protein immunoreactivity." (PMID 41218617, 2025). "ACTN4 gene amplification is related to poor prognosis and tumor chemoresistance in patients with ovarian cancer." (PMID 32670437, 2020). "Published proteomics and molecular biology studies suggest up-regulation of ACTN4, CRKL, GELS, HSPA8, talin-1, tubulins and WDR1 in ovarian cancer." (PMID 29344361, 2018).
glioma (8 papers, 2010 to 2026). A benign or malignant brain and spinal cord tumor that arises from glial cells (astrocytes, oligodendrocytes, ependymal cells). "The network topology analysis performed in this study revealed a set of central nodes associated to glioma malignancy, such as Map3k14, Mapk1, Actn4, Hspa5, Atf2, Rac1,E2f1, Shc1, Pik3ca, Akt1, Vim and Egr1." (PMID 26582089, 2015). "Furthermore, the highly expressed CHI3L1 in gliomas enhances NF‐κB signalling by facilitating the translocation of NF‐κB subunits through binding to ACTN4 and NFKB." (PMID 38809929, 2024). "Indeed, current findings and our results showed that the downregulation of ACTN4 significantly affected the expression of myosin II in Glioma and MYH10 and myosin light chain (MLC2) in fibroblasts." (PMID 21085685, 2010). "As recent reports showed that the reduced contractility of glioma in which ACTN4 has been significantly downregulated with siACTN4 RNA was due to the decreased expression of myosin II, we determined the expression of myosin II in both WT ACTN4 and ACTN4 KD murine lung fibroblasts." (PMID 21085685, 2010). "Chitinase-3 like-protein-1 (CHI3L1) binds to actinin alpha 4 (ACTN4) and NF-κB1 and enhances the NF-κB signaling by promoting the NF-κB subunit nuclear translocation to facilitate glioma progression." (PMID 39353894, 2024). "Intriguingly, CHI3L1 binds to actinin alpha 4 (ACTN4) and NFKB1, and enhances the NF-κB signaling pathway by promoting the NF-κB subunit nuclear translocation in glioma cells." (PMID 36276655, 2022). "The Pearson correlation analysis indicated that strong positive correlations occurred between CHI3L1 and ACTN4, NFKB1 or NFKB2 in TCGA and CGGA glioma cohorts." (PMID 36276655, 2022). "The top-ranking genes were related to the TRIP10, NR2F6, ACTN4, SBNO2, and TGFB1L1 genes (p < 0.05), and a link between ACTN4 and TGFB1L1 expression and tumorigenesis was shown in glioma samples." (PMID 34722629, 2021).
lymph node metastasis (7 papers, 2014 to 2025). "The serum ACTN4 levels were significantly associated with the FIGO stage, lymph node metastasis, and lymphovascular space invasion of CC, which suggests that ACTN4 could contribute to the development, invasion, and metastasis of CC." (PMID 32855746, 2020). "Serum ACTN4 levels were associated with the FIGO stage, lymph node metastasis, and lymphovascular space invasion of CC (all P < 0.05)." (PMID 32855746, 2020). "In conclusion, our study showed that serum ACTN4 levels were increased in CC patients and were related to the FIGO stage, lymph node metastasis, and lymphovascular space invasion of CC patients." (PMID 32855746, 2020). "We observed that serum ACTN4 levels were related to the FIGO stage, lymph node metastasis, and lymphovascular space invasion (all P < 0.05)." (PMID 32855746, 2020). "Univariate Cox regression analyses showed that the serum ACTN4 levels (P < 0.001), FIGO stage (P < 0.001), differentiation degree (P = 0.012), lymph node metastasis (P < 0.001), and lymphovascular space invasion (P = 0.024) had significant prognostic value for OS." (PMID 32855746, 2020). "We calculated the hazard ratios (HR) of some parameters, including age, gender, size, lymph node metastasis, histological grade, neural invasion, vascular invasion, actinin-4 protein expression, and CNI of ACTN4, for death by using univariate and multivariate Cox regression analysis." (PMID 24574362, 2014).
end-stage renal disease (6 papers, 2004 to 2026). "Mutations in ACTN4, which encodes an Actin-filament crosslinking protein, caused idiopathic FSGS with autosomal dominant inheritance in three families suffering from increased urinary protein excretion and decreased kidney function, with ultimate progression to end-stage renal failure." (PMID 35265622, 2022).
Hypertension (6 papers, 2023 to 2025). The presence of chronic increased pressure in the systemic arterial system. "ACTN4, our top hit, was recently associated with vasorelaxation, a mechanism that can lead to hypertension when malfunctioning." (PMID 37131961, 2023). "Single nucleotide polymorphisms in ACTN4 are associated with hypertension in GWAS, suggesting it may regulate renal NaCl reabsorption or affect blood pressure by regulating overall renal function." (PMID 39446130, 2024). "This is important because SNPs in ACTN4 are associated to hypertension in the general population and it is possible that ACTN4 is also involved in hypertension by modulating the ALMS1-NKCC2 interaction or acting independently on ALMS1 on NKCC2 to mediate its endocytosis." (PMID 39717823, 2024). "For example, proteins important for vascular structure (FLNA) and calcium regulation (ACTN4) were up-regulated, and mitochondrial function (COX6B1) was down-regulated, in human hypertension." (PMID 38879891, 2024).